TBX5 (T-box transcription factor 5)
Diseases named in the same sentence as TBX5 in open-access papers (continued):
Sharing a sentence is not in itself a finding about the gene and the disease.
cutaneous melanoma (2 papers, 2021). A primary melanoma arising from atypical melanocytes in the skin. "This study is helpful for the understanding of the biological functions of the microRNA-603/TBX5 regulatory axis in the occurrence of tumors, which is expected to offer a new target for the molecular therapy of cutaneous melanoma." (PMID 35003317, 2021). "In summary, in this study, it was manifested that microRNA-603 was remarkably upregulated in cutaneous melanoma cells, and it played a role as a cancer-promoting factor by targeting and regulating TBX5 expression." (PMID 35003317, 2021). "This study conducted an in-depth investigation on the expression levels of microRNA-603 and TBX5 in cutaneous melanoma and their influence on the development of melanoma cells." (PMID 35003317, 2021). "The mRNA and protein expression levels of TBX5 in cutaneous melanoma cell lines were tested by qRT-PCR and western blot, respectively." (PMID 35003317, 2021). "Based on the expression status of microRNA-603 and TBX5, and the binding interaction between them, we proposed the microRNA-603/TBX5 axis in cutaneous melanoma." (PMID 35003317, 2021). "TBX5 was downregulated in cutaneous melanoma cells, and its expression level was modulated by microRNA-603." (PMID 35003317, 2021). "MicroRNA-603 could regulate the expression of TBX5, thus promoting the malignant progression of cutaneous melanoma cells." (PMID 35003317, 2021). "On the contrary, patients with skin cutaneous melanoma having high expression of TBX5 might possess a better prognosis." (PMID 34900441, 2021). "In addition, TBX5 was lowly expressed in cutaneous melanoma cells." (PMID 35003317, 2021). "In addition, the interaction between microRNA-603 and TBX5 was determined by dual-luciferase reporter gene assay, and their impacts on the growth of cutaneous melanoma cells were detected by cellular function experiments such as MTT, colony formation, and Transwell assays." (PMID 35003317, 2021).
Down syndrome (2 papers, 2015 to 2020). "Genetic defects of Nkx 2–5, GATA4, Tbx5 and Downs syndrome are known to be linked with ASD pathogenesis." (PMID 33250054, 2020).
Hyperglycemia (2 papers, 2024 to 2025). An increased concentration of glucose in the blood. "TBX5 is possibly the main factor involved in fetal heart malformation induced by hyperglycemia." (PMID 38892128, 2024). "In-utero exposure to maternal hyperglycemia or hypoxia can interfere with cardiac looping and septation via dysregulation of NKX2.5, GATA4, and TBX5 gene expression." (PMID 41383574, 2025).
Hypertension (2 papers, 2021 to 2024). The presence of chronic increased pressure in the systemic arterial system. "From the DO analysis, the following potential gene targets have been selected, these include CLCNKB, CYPB11B2, SH2B2, STK9, and TBX5 as they show interactions exclusively with hypertension-related pathways." (PMID 33917487, 2021).
melanoma (2 papers, 2021 to 2024). A malignant, usually aggressive tumor composed of atypical, neoplastic melanocytes. "First, we investigated the transcriptional activity of PAX3 or TBX5 in the melanoma cell lines SBcl2, WM1366 and MV3 using reporter gene assays." (PMID 38388496, 2024). "Firstly, transfection groups of the melanoma cell line A375 were constructed, including the inhibitor NC+si-NC, microRNA-603 inhibitor+si-NC, and microRNA-603 inhibitor+si-TBX5 groups." (PMID 35003317, 2021). "Then, in order to better verify the correlation between microRNA-603 and TBX5 as well as their effects on melanoma cell behaviors, a series of cellular function experiments were conducted." (PMID 35003317, 2021). "First, qRT-PCR and western blot results manifested that compared with the normal human melanocyte cell line, TBX5 expression in melanomas was downregulated." (PMID 35003317, 2021). "Nevertheless, the molecular modulatory mechanism of TBX5 in melanoma remains unclear." (PMID 35003317, 2021).
Obesity (2 papers, 2011 to 2025). Accumulation of substantial excess body fat. "In the 12q24 area there are other genes that might be involved in the phenotype including THRAP2, TBX5 and PTPN11 for cardiac and great vessel anomalies; TBX5, CMKLR1, and TRPV4 for skeletal defects; PRKAB1, GPR109A, and GPR109B for increased hunger and obesity." (PMID 21457577, 2011).
albinism (1 paper, 2022). A congenital disorder characterized by partial or complete absence of melanin pigment in the eyes, hair, or skin. "We have shown that albinism and heart defects could be easily identified upon direct disruption of tyr and tbx5, respectively, in X. tropicalis embryos." (PMID 35804405, 2022).
Amelia (1 paper, 2025). Congenital absence (aplasia) of one or more limbs. "To date, TBX5 has been associated with upper amelia, TBX4 with lower amelia, and WNT3, WNT7A and RSPO2 with tetra-amelia syndromes in humans (and cattle, for RSPO2)." (PMID 40131457, 2025).
Anophthalmia (1 paper, 2012). Absence of the globe or eyeball. "However, our Tbx5 over-expressing embryos showed particularly severe eye defects such as asymmetrically positioned eyes, fusion of eyes, and even unilateral anophthalmia." (PMID 23226307, 2012).
Baller-Gerold syndrome (1 paper, 2021). Baller-Gerold syndrome is characterized by the association of coronal craniosynostosis with radial ray anomalies (oligodactyly, aplasia or hypoplasia of the thumb, aplasia or hypoplasia of the radius). "In humans, ESCO2, TBX5, and RECQL4 cause Roberts, Holt–Oram, and Baller–Gerold syndromes, respectively." (PMID 34249098, 2021).
Bicuspid aortic valve (1 paper, 2022). The presence of an aortic valve with two instead of the normal three cusps (flaps). "Recently, disease modeling of GATA4 and TBX5 pathogenic variants in human iPSC-derived CM and iPSCs-derived EC from patients with bicuspid aortic valve and calcific aortic valve disease with NOTCH1 haploinsufficiency have predicted that CHD-linked GRN is sensitive to gene dosage." (PMID 35970860, 2022).
bladder urothelial carcinoma (1 paper, 2021). "The same was true for TBX5 in kidney renal clear cell carcinoma, UCEC, and bladder urothelial carcinoma." (PMID 34900441, 2021).
channelopathy (1 paper, 2024). Channelopathies are a group of diseases caused by the dysfunction of ion channel subunits or their interacting proteins. "The variants included three channelopathy-associated genes (RYR2, CACNA1C, and ANK2), three HCM- or DCM-associated genes (MYH7, LDB3, and PRKAG2), five ACM-related genes (PKP2, JUP, DSG2, DSP, and TMEM43), and two cardiac transcription factor genes (TBX5 and GATA4)." (PMID 39272661, 2024).
coloboma (1 paper, 2018). An abnormality in which a part of a structure in one or both eyes is missing. "We found that depletion of kdm5c significantly downregulated vax1, vax2, pax6 expressions, while tbx5 expression was slightly reduced; thus, the reduced expression of DV-patterning markers may be responsible for the colobomas observed in kdm5c morphants." (PMID 30522514, 2018).
depression (1 paper, 2018). "Alterations of miR‐10‐5p after transfection with its mimic and inhibitor caused the related depression and re‐expression of TBX5 and inflammatory factors in SW982 cells." (PMID 28782180, 2018).
endometrial cancer (1 paper, 2019). Primary or metastatic malignant neoplasm involving the endometrium (mucous membrane that lines the endometrial cavity). "We tested the effectiveness of the methylation status of four genes (BHLHE22, CDO1, TBX5, and HAND2) in endometrial cancer detection." (PMID 31779688, 2019).
Fanconi anaemia (1 paper, 2018). "A genetic testing for TBX5, 22q11.2, microdeletion and Fanconi anaemia might be needed for final diagnosis." (PMID 29855495, 2018).
glioblastoma (1 paper, 2025). The most malignant astrocytic tumor (WHO grade IV). "Many of the identified differentially expressed genes are understudied in glioblastoma; however, several are key regulators of tissue remodeling (MFAP4 and ALX4), mesoderm development (TBX5 and ALX4), and immune modulation (FUT2, C4BPA, MFAP4, and GRM4)." (PMID 41066027, 2025).
laryngeal squamous cell carcinoma (1 paper, 2022). A squamous cell carcinoma that arises from the larynx. "In a genome-wide association study involving 993 laryngeal squamous cell carcinoma patients and 1,995 controls, researchers found the three most significant SNPs—rs174549, rs2857595, and rs10492336—which are located in FASD1, AIF1, and TBX5 genes, respectively." (PMID 35530357, 2022).
lung squamous cell carcinoma (1 paper, 2024). "Then we used Human Protein Atlas to determine the expression of TBX2, TBX3, TBX4 and TBX5 in lung squamous cell carcinoma tissues." (PMID 38413457, 2024).
non-small cell lung carcinoma (1 paper, 2018). A group of at least three distinct histological types of lung cancer, including non-small cell squamous cell carcinoma, adenocarcinoma, and large cell carcinoma. "This apparent contradiction finding is however corroborated by recent studies in different cancer cell lines, including non-small cell lung carcinoma (NSCLC) cell lines where overexpression of TBX5 was shown to suppress cell proliferation, colony formation, and invasion and to induce apoptosis." (PMID 30425966, 2018).
polydactyly (1 paper, 2020). A disease characterized by the presence of polydactyly, including syndromic and non-syndromic forms. "To identify the genetic characteristics of complex CHD and polydactyly with emphasis on whether TBX5 was involved, we performed whole exome sequencing (WES) on blood sample of a patient with complex CHD and polydactyly who had successful surgical repair." (PMID 33098376, 2020).
pulmonary hypertension (1 paper, 2022). Increased pressure within the pulmonary circulation due to lung or heart disorder. "In the Human Lung Cell Atlas project, lung pericytes are identified using COX4I2, TBX5, and KCNK3 and its potential implication in pulmonary hypertension is proposed." (PMID 35722109, 2022).
right ventricular dilation (1 paper, 2026). "Depletion of a single Tbx5 allele in addition to both Tbx4 alleles exacerbated histologic phenotypes, with worsened right ventricular dilation." (PMID 42044173, 2026).
seminoma (1 paper, 2025). A radiosensitive malignant germ cell tumor found in the testis (especially undescended), and extragonadal sites (anterior mediastinum and pineal gland). "There is no established association between the TBX5 gene and the development of seminoma or other forms of testicular cancer." (PMID 39809819, 2025). "However, it is difficult to determine the differences between TBX5 abundance in seminomas vs. non-seminomas in The Human Protein Atlas." (PMID 39809819, 2025).
cancer (33 papers, 2013 to 2025). A tumor composed of atypical neoplastic, often pleomorphic cells that invade other tissues. "Genetic variants and altered expression levels of TBX5 gene have been reported in patients with cancers." (PMID 31775637, 2019). "TBX5 is an oncogene and is associated with cancer cell apoptosis." (PMID 38965548, 2024). "The suppressed Wnt signaling may be associated with the formation of YAP, β‐catenin, and TBX5 complex that is essential for transformation and survival of β‐catenin‐driven cancers." (PMID 29316250, 2018). "This creates a mutual activation loop among Tbx2, Tbx3, and Tbx5, with the notable exception that Tbx3 represses Tbx2, as was reported for cancer cells." (PMID 41278973, 2025). "This is important, as, if TBX3 proved to be dispensable for homeostasis as BCL9/9L but required for cancer cell survival as TBX5 or β-catenin, its targeting will constitute the proverbial therapeutic window." (PMID 40343989, 2025). "By phosphorylation of YAP, YES1 regulates the formation, localization and activity of the YAP-β-Catenin-TBX5 complex, thereby promoting the survival and transformation of β-catenin-active cancer cell lines." (PMID 33158300, 2020). "TBX5 regulates cell proliferation during cardiogenesis and it is related to cell migration as well as cell proliferation in cancers." (PMID 26035298, 2015). "YAP1/β-catenin promote cancer cell proliferation and tumorigenesis via TBX5 but also promote overgrowth of the heart through binding to TEAD." (PMID 26549256, 2015). "However, in the microRNA-603 inhibitor+si-TBX5 transfection group, the migratory and invasive abilities of cancer cells were significantly restored." (PMID 35003317, 2021). "Studies confirmed that TBX5 plays a part in suppressing cancer in a variety of cancer tissues." (PMID 35003317, 2021). "The function of TBX5 in cancer development is largely unclear." (PMID 31779688, 2019). "TBX5 plays an important role in tissue development and Cancer." (PMID 28782180, 2018). "Additionally, YAP and TAZ have been reported to bind other transcription factors, including TBX5 8, 51, which has been identified as an important interaction in cancer." (PMID 27184927, 2016). "We propose that the interplay of Wnt and Hippo signaling pathways could regulate target genes, coding or non-coding, by the β-catenin/YAP/TBX5 transcription complex in cancer cells." (PMID 26415221, 2015). "The constructed TF and miRNA regulatory networks showed that hub nodes including miR-126-3p, miR-30c-2-3p, HOXA5, MEIS1 and TBX5 were markedly different in two separate TF and miRNA enrichment analyses, and their levels were significantly decreased in cancer tissues." (PMID 26035298, 2015). "The expression of T-box transcription factor 5 (TBX5) has previously been observed in human cancer." (PMID 26622790, 2015). "Wnt/β-catenin signaling and the Hippo pathway might be interconnected by sharing a transcriptional complex, as proposed for β-catenin/YAP/TBX5 to be important for tumor cell survival and tumorigenesis in β-catenin-driven cancer." (PMID 26415221, 2015). "In addition, TBX5 may exert its inhibitory effects on cancer cells by targeting the extrinsic pathway, apoptotic gene BAX, and Granzyme A signaling cascade to induce apoptosis." (PMID 38965548, 2024). "However, the role of TBX5 in malignancy progression in cancer still remains elusive." (PMID 38413457, 2024). "In addition to TEAD family members, TBX5 is known to be correlated with YAP1 by forming a complex with YAP and β‐Catenin in initiating the expression of BIRC5 that encodes Survivin and is crucial for cancer cell survival." (PMID 35000271, 2022). "Other transcription factors (TP73, ERBB4, TBX5 and RUNX3) detected variations across cell lines, with TP73 being notably upregulated in four cancer lines except for SqCC/Y1." (PMID 35000271, 2022).
cancer (continued). "We observed that 18 genes revealed a significant negative correlation (FDR < 0.01, Spearman's rho < -0.3) in at least five cancer types, except for ADCY8 and TBX5, which showed a cancer-type specific methylation driver." (PMID 33859751, 2021). "Except for TBX5, all 5 genes (GFRA1, SLC6A5, SOX1, SOX14 and TBX20) were significantly differentially methylated between normal and cancer tissues with a high methylation frequency in both ADC and SCC." (PMID 27738327, 2016). "In a separate study, β-catenin-active cancers were reported to be dependent on a signaling pathway involving the transcriptional regulator YAP1 and the transcription factor TBX5, both of which form a complex with β-catenin." (PMID 26134786, 2015). "We surveyed a TBX5-mediated gene network and found that it comprised up-regulated expression of baculoviral IAP repeat containing 5 (BIRC5), a member of the inhibitor of apoptosis (IAP) family that plays crucial anti-apoptotic roles in cancer." (PMID 28978111, 2017). "So we tested whether the oncogenic signaling pathways, Wnt/β-catenin and Hippo/YAP pathways, are relevant to the enhanced expression of RMRP in cancer cells because of the predicted β-catenin/TCF and YAP/TBX5 elements in the upstream regions of the RMRP gene." (PMID 26415221, 2015). "However, in cancer cells Wnt stimulation increases the protein level of β-catenin and YAP in the nucleus and recruits them to the promoter regions of the RMRP gene via TCF4 and TBX5 DNA binding proteins, which leads to elevated transcription of RMRP." (PMID 26415221, 2015).
tumor (32 papers, 2011 to 2025). "TBX5 is part of the T-box gene family and is thought to upregulate tumour cell proliferation and metastasis when mutated." (PMID 23984174, 2013). "In cervical cancer, miR-10a-5p promotes angiogenesis and tumor progression by activating Hedgehog signaling through the downregulation of TBX5." (PMID 39796267, 2025). "miR-10a-5p promotes tumor growth and angiogenesis by activating Hedgehog signaling through the downregulation of TBX5." (PMID 39796267, 2025). "YAP1 and TBX5 form a complex with β-catenin, which localizes to the promoter of anti-apoptotic genes, enhancing their anti-apoptotic effects in tumor cells." (PMID 38965548, 2024). "We also provide evidence suggesting stark differences between the path to T cell dysfunction in ccRCC and that in other tumor types or in chronic infection at the level of TFs (for example, TBX5) and surface markers (for example, CD101)." (PMID 35668194, 2022). "As the literature review illustrated, TBX5 is a tumor suppressor and can be downregulated by some oncomicroRNAs." (PMID 35003317, 2021). "For example, Cul4A was reported to activate ZEB1 in tumor progression and tbx5 expression in zebrafish development by promoting H3K4 methylation." (PMID 31101894, 2019). "The distribution of TBX2 and TBX5 was examined in formalin-fixed paraffin-embedded tissue sections from tumor-free regions of the lung." (PMID 30425966, 2018). "TBX5 was expressed in a nuclear and cytoplasmic pattern in tissues, and TBX5 protein expression was observed in the tumor tissue." (PMID 26622790, 2015). "In the present study, RT-qPCR analysis was used to determine that the mRNA level of TBX5 was reduced in normal paracancerous tissues compared with stage I and II GC tumor tissues (P<0.01)." (PMID 26622790, 2015). "The TBX5 mRNA expression levels were increased in GC stage I and II tumor tissues (P=0.01, n=30) compared with the matched adjacent non-tumor tissue." (PMID 26622790, 2015). "TBX5 and YES-associated protein 1 (YAP1) form a complex with β-catenin, which localizes and activates BCL2 Like 1 (BCL2L1) and Baculoviral IAP Repeat Containing 5 (BIRC5), thereby enhancing the anti-apoptotic effect on tumor cells." (PMID 38965548, 2024). "In addition, tumor biomarkers such as expression of NOTCH1, tumor hypoxia, and genetic variants in genes such as TGFβ1, COX7A1, and TBX5 have also been shown to be associated with prognosis in HPV-related HN cancer." (PMID 34830844, 2021). "Moreover, TBX5, one of the most important genes for tumor classification from the previous study, could be regulated by one of the 5 most frequently appearing 5’isomiRs in our sets (miR-10b-5p/5’isomiR-39) as derived from the TargetScanHuman prediction." (PMID 30732570, 2019). "They survive for long periods of time and tightly maintain the gene expression of differentiation genes such as Tbx5, GATA4 that interact with tumor suppressors (TS) and exert TS like effect." (PMID 38110859, 2023). "Among them, we identified and experimentally confirmed a group of methylation driver genes (e.g., PCDH17, IRX1, TBX5 and HSPB6) that play a critical role in neoplasia initiation, promotion, and progression." (PMID 33859751, 2021). "The transcriptional coactivator YAP, together with the transcription factor TBX5, has been shown to regulate FGFR1 expression in other tumor types." (PMID 31963871, 2020). "Comparison of primary tumor and metastasis cells from the same patient revealed up‐regulation of RELN and TBX2,TBX4 and TBX5 genes and down‐regulation of several HOXD genes." (PMID 29542868, 2018). "In these tumor cells, YAP1 forms a complex with TBX5 (T-box 5, a transcription factor)." (PMID 36532767, 2022). "Indeed, autophosphorylation at Y357 leads to assembly of YAP with T-box transcription factor 5 (TBX5) in nucleus, which in turn promotes the β-catenin-mediated tumor formation." (PMID 34345207, 2021).